OR2M4 (olfactory receptor family 2 subfamily M member 4)
Description:
Odorant receptor.
Synonyms: HTPCRX18; TPCR100; HSHTPCRX18; OST710; OR1-55
Tractability: Antibody: UniProt places it where antibodies can reach, with medium confidence; UniProt predicts a signal peptide or a membrane-spanning region; its Gene Ontology location is reachable by antibodies, with medium confidence.
Gene: Protein-coding gene on chromosome 1 (248,231,417 to 248,244,679, forward strand). Ensembl gene ENSG00000171180.
Subcellular location: Cell membrane
Pathways (Reactome):
Sensory Perception: Expression and translocation of olfactory receptors
Gene Ontology:
Molecular function: olfactory receptor activity; G protein-coupled receptor activity
Biological process: detection of chemical stimulus involved in sensory perception of smell; sensory perception of smell; G protein-coupled receptor signaling pathway
Cellular component: membrane; plasma membrane
Genetic constraint (gnomAD): Loss-of-function variants: 11 observed, 16.03 expected, observed/expected ratio (o/e) 0.69, 90% interval 0.43 to 1.14. The upper end of that interval is the gene's LOEUF score, 1.14, which puts it in group 4 of 6, group 1 being the genes least tolerant of losing a copy. Missense variants: 374 observed, 402.6 expected, observed/expected ratio (o/e) 0.93, 90% interval 0.85 to 1.01. Synonymous variants: 152 observed, 149.39 expected, observed/expected ratio (o/e) 1.02, 90% interval 0.89 to 1.16.
Homologues: Orthologues: chimpanzee OR2M4 (99% identical), macaque OR2M4 (95% identical), pig OR2M4 (85% identical), guinea pig OR2M4 (79% identical). Paralogues in human: OR2M3 (74% identical), OR2M5 (74% identical), OR2M2 (74% identical), OR2M7 (73% identical), OR2T33 (56% identical), OR2T8 (55% identical), OR2T12 (55% identical), OR2T2 (55% identical), OR2T35 (55% identical), OR2V1 (55% identical), OR2V2 (54% identical), OR2T27 (52% identical), and 80 more.
Diseases named in the same sentence as OR2M4 in open-access papers:
OR2M4 is named in the same sentence as 1 disease in open-access papers, as found by Europe PMC text mining. Sharing a sentence is not in itself a finding about the gene and the disease. The quoted sentences say what the papers report.
metastatic melanoma (1 paper, 2021). A melanoma that has spread from its primary site to another anatomic site. "CYT-high metastatic melanomas had recurrent copy number amplifications in loci 1p12 (NOTCH2), 1q44 (OR2M4), 7q36.1 (KCNH2), 11q13.3 (FGF3/4), 12p11.23 (MED21) and 12q13.3 (R3HDM2) and deletions in 1p22.1 (RHOC, NRAS), 9p21.3 (CDKN2B), 10q23.2 (miR346), 11q23.3 (ATM, CHEK1, ETS1) and 15q15.3 (CASC4)." (PMID 33779796, 2021).